RN7SKP31 (RN7SK pseudogene 31)
Gene: Miscellaneous RNA gene on chromosome X (138,397,351 to 138,397,628, forward strand). Ensembl gene ENSG00000252163.
Homologues: Orthologues: chimpanzee 7SK (99% identical), mouse Gm54436 (50% identical), guinea pig 7SK (43% identical). Paralogues in human: RN7SKP162 (58% identical), RN7SKP149 (57% identical), RN7SKP103 (56% identical), RN7SKP177 (56% identical), RN7SKP255 (56% identical), RN7SKP78 (56% identical), RN7SKP171 (56% identical), RN7SKP217 (56% identical), RN7SKP25 (56% identical), RN7SKP275 (56% identical), RN7SKP126 (55% identical), RN7SKP230 (55% identical), and 284 more.